TERT (telomerase reverse transcriptase)
Diseases named in the same sentence as TERT in open-access papers (continued):
Sharing a sentence is not in itself a finding about the gene and the disease.
cancer (continued). "The reason for the strong differences of mutational frequencies of TERT between cancer entities is not well understood." (PMID 34200508, 2021). "Across the 141 cross-cancer associations, pleiotropic variants were most commonly found in TERT-CLPTM1L (16% versus 3.0%) and HLA (6p21.32: 16% versus 3.6%; 6p21.33: 13% versus 3.6%)." (PMID 33579919, 2021). "The data presented here are in keeping with most reports that the TERT promoter hypermethylation is positively associated with the TERT expression and telomerase activity in cancers." (PMID 35155512, 2021). "One of the recent examples was a study focusing on cancer-specific TERT promoter mutations which are observed in ~ 19% of the cancers but not in healthy tissues." (PMID 33599797, 2021). "TERT promoter mutations produce the ETS transcription factor family binding sites in multiple cancer types." (PMID 34947936, 2021). "This argues that this mutation has very little impact on TERT expression in 2XSB cells, despite the fact that this mutation alters TERT expression in other cancer types." (PMID 33707600, 2021). "In conclusion, the present study reveals a novel mechanism underlying synergistic effect of BRAFV600E and TERT promoter mutations, two hotspot genetic altercations in human cancers, on TERT reactivation." (PMID 33483600, 2021). "For these reasons, the expression of telomerase or TERT is considered as a hallmark of cancer, which enables replicative immortality." (PMID 34395278, 2021). "Point mutations in the TERT promoter occur at a high frequency in multiple cancers, including urothelial cancer (UC)." (PMID 33854611, 2021). "Epigenetic alteration of the TERT promoter is strongly linked to its regulation in stem and cancer cells." (PMID 33802026, 2021). "These mutations are predicted to increase TERT expression levels, enzymatic activity, and telomere length; they are also associated with decreased survival in cancer patients." (PMID 34439356, 2021). "Promoter mutations of the telomerase reverse transcriptase (TERT) gene are heavily implicated in human cancers, as they convey increased TERT expression, which in turn promotes immortalization." (PMID 33269427, 2021). "In FTC and PTC, TERT promoter mutation is significantly associated with patients’ age, cancer size, presence of ETE, vascular invasion, LNM, distant metastases, advanced tumor stage, persistence, or recurrence, and disease-specific mortality." (PMID 34684168, 2021). "TERT is an important driver gene in many cancers, and a previous study suggests that TERT is overexpressed by point mutations, SVs, copy number alternations, and HBV integrations." (PMID 33910608, 2021). "Naturally occurring HLA-II-restricted CD4 T cell responses against TERT peptides were detected in patients with various types of cancer and were associated with a good prognosis." (PMID 34144673, 2021). "TERT, a well-known tumor-associated antigen, is an enzyme responsible for the synthesis of telomeres, activated/overexpressed in many cancer cells." (PMID 34067686, 2021). "In human cancers, TERT promoter mutations have been shown to define a subpopulation of patients with a poor prognosis." (PMID 34261460, 2021). "In contrast, the correct identification of both RAS and TERT mutation would yield a high probability of high-risk cancer." (PMID 32948110, 2021). "TERT promoter (TERTp) mutations have been identified as one of the mechanisms responsible for telomerase re-expression in cancer, being described for the first time in melanoma." (PMID 32659948, 2020). "The presence of TERT promoter mutations has been associated with increased TERT expression, cancer recurrence, and treatment resistance." (PMID 32630460, 2020).
cancer (continued). "They document a highly conserved pattern of hypomethylation around the proximal promoter, as well as a more heterogeneous region of hypermethylation further upstream, both associated with active TERT expression in cancer cells." (PMID 32920953, 2020). "Consistent with the findings of Stern and colleagues, we find that in cancers with TERT promoter mutations, the expressed allele is the mutant allele while the silenced allele is WT." (PMID 32468444, 2020). "In the past decade, it became apparent that in numerous cancer types the TERT promoter carries mutations." (PMID 32630460, 2020). "These include alterations that are common across multiple cancers, such as aneuploidy, TERT mutations, and activation of the RAS-RAF-MEK-ERK/JNK and PI3K/AKT/mTOR pathways." (PMID 32485873, 2020). "These analyses confirmed allele-specific hypomethylation of mutant alleles compared to WT alleles in cancer cell line models with C228T or C250T TERT promoter mutations, namely, LOX-IMVI, M14, SNB19 and TSU-PR1." (PMID 32468444, 2020). "For example, mutations in the TERT promoter region frequently occur in diverse types of cancers, and mutations in these hotspots create de novo-binding sites of oncogenic transcription factors in ETS family genes." (PMID 31474751, 2020). "Surprisingly, it has also been described that mutations of the TERT gene are of paramount importance for cancer cells derived from tissues with low rates of cellular regeneration." (PMID 32899768, 2020). "TA becomes activated in cancer cells by mechanisms including chromosome rearrangements, epigenetics and TERT promoter mutations (TPMs)." (PMID 32575418, 2020). "Our findings suggest that hypermethylation of the TERT promoter alleles signals transcriptional repression of those alleles, leading to attenuation of TERT activation in cancer cells." (PMID 32468444, 2020). "Yet, the possibility of an underlying TERT activation mechanism that is necessary, specific, and universal to cancer cells is noteworthy." (PMID 33245585, 2020). "In the past two decades, remarkable progress has been made in understanding the underlying mechanisms of TERT upregulation in cancers." (PMID 33061812, 2020). "Remarkably, these are so frequent that TERT promoter mutations are the most frequent mutations in the cancer genome." (PMID 32630460, 2020). "Considering central role of TERT in oncogenesis, numerous studies have discussed the association between cancer susceptibility and SNPs in TERT, and accumulated evidences have suggested significant association between two sides." (PMID 32694935, 2020). "TERT dynamic subcellular localization is particularly crucial in the context of cancer, as evidenced by the observation that TERT bearing mutations in the NES motif cannot immortalize cells despite intact catalytic activity." (PMID 32599885, 2020). "Another important example is the TSS site in TERT, which ranked fifth in our results (P = 1.55 × 10−10) and has been experimentally validated to be associated with multiple types of cancer progression." (PMID 33092526, 2020). "There are several mechanisms underlying TERT activation with TERTp somatic mutations being the most widely studied in many cancer types since their discovery in 2013." (PMID 32560331, 2020). "This suggests that TERT reactivation on one allele is probably sufficient to ensure telomere maintenance or elongation in cancer cells." (PMID 32204305, 2020). "Here, we have designed a new variant of cancer vaccine against TERT, an expression-optimized DNA encoding rat TERT." (PMID 32570805, 2020). "Another open question concerns the role of TERT promoter mutations or TERT amplifications, with their associated increase in telomerase expression, often present in aggressive or advanced cancer." (PMID 32920953, 2020). "These mutations represent one possible explanation for TERT expression and telomerase reactivation in cancer cells, which can ultimately lead to cell immortalization." (PMID 32932803, 2020).
cancer (continued). "Telomerase can be reactivated by gain-of-function Telomerase Reverse Transcriptase (TERT) promoter mutations (TPMs) that occur in several cancer subtypes with high incidence and association with diagnosis, prognosis and epigenetics." (PMID 32575418, 2020). "And, over two-thirds of the telomerase positive cancers (15/21) showed expression of the full-length TERT transcript, higher telomerase activity and were associated with a significantly shorter patient survival time." (PMID 32849278, 2020). "TERT mutations have frequently been detected in many cancers, and in our study, a damaging promoter variant was consistently present in 33% of patients and in 41% of recurrences." (PMID 32455687, 2020). "In conclusion, our findings suggest that hypermethylation of TERT promoter alleles signals transcriptional repression of these alleles, leading to attenuation of TERT activation in cancer cells." (PMID 32468444, 2020). "In cancer cells, the telomerase expression is increased by amplification and mutations of the TERT and TERC genes, changes in the methylation status of their promoters." (PMID 32599754, 2020). "In cancers with TERT promoter mutations, the expressed allele is mutated, while the WT allele is silenced." (PMID 32722302, 2020). "Gene therapy by administering TERT using an adeno-associated virus can be more effective and have a low risk of cancer." (PMID 32599754, 2020). "Further, the TERT locus has also been found to have multiple chromosomal copies or, be amplified in cancer with associated increased TERT transcription." (PMID 32849278, 2020). "Two such human cancer-associated hot spot TPMs are cytidine-to-thymidine changes at genomic loci Chr5:1,295,228 (C228T) and 1,295,250 (C250T), located upstream of TERT transcription and translation start." (PMID 32575418, 2020). "In cancer cell lines, only the mutant TERT alleles are expressed, which indicates that the promoter mutation created a de novo transcription factor binding site and activated transcription and expression in the mutant allele." (PMID 31474751, 2020). "Three different mutations were identified in the promoter of TERT, one in the core promoter (9.7%), that was also the most frequently found in cancers, and two in the 5′‐untranslated region (UTR) of TERT mRNA (1.9% and 0.4%)." (PMID 32083805, 2020). "TERT mutations include multiple cancer‐specific genetic alterations, such as TERT promoter mutations,17, 18TERT amplification,19TERT rearrangements, and TERT transcriptional activation." (PMID 32810393, 2020). "This included cell lines with the −124 or −146 activating promoter mutation as well as wild‐type TERT cancer lines." (PMID 33245585, 2020). "The TERT gene encodes the catalytic subunit of the telomerase complex and the reactivation of TERT expression is a hallmark of cancer." (PMID 32882916, 2020). "In contrast to other cancers, mutations in the TERT promoter region are rare in NB primary tumors and cell lines and TERT activation is most likely achieved by amplification or juxtapositions of TERT to strong enhancer elements." (PMID 32309213, 2020). "TERTp mutations are also less frequent in cancers where viral transformation or viral oncogenes reactivate TERT transcription, such as HBV-DNA or high-risk HPV16/18 E6." (PMID 32204305, 2020). "Recently, TERT promoter mutations have been described to stimulate the TERT transcription or telomerase activation in several types of cancers including HCC7." (PMID 32424223, 2020). "Elevated expression of human telomerase reverse transcriptase (TERT) is an important hallmark in cancers, but the mechanism by which TERT is activated differentially in cancers is poorly understood." (PMID 33239622, 2020).
cancer (continued). "We further analyzed the frequency of TERT mutations between different sex groups in different cancer types." (PMID 32915164, 2020). "Telomerase activation occurs in 85-90% of all human cancers 6, 7, and activation or upregulation of TERT gene expression is the leading cause of its activation." (PMID 33061812, 2020). "For example, TERT‐activating mutations are more prevalent in some types of cancers (e.g., melanoma and medulloblastoma)." (PMID 33245585, 2020). "We further explored the predictive value of TERT mutation on the efficacy of anti‐CTLA4 treatment in certain cancer types." (PMID 32810393, 2020). "Abnormal high expression of TERT was discovered and usually associated with advanced stages or poor prognosis in various cancers." (PMID 33061812, 2020). "On the one hand, hypermethylation of a small cluster of CpG dinucleotides upstream of the TERT transcriptional start site (TSS) has been implicated in conferring activation of TERT expression in cancer." (PMID 32468444, 2020). "Recently, in order to further delineate TERT transcriptional regulation, studies have been conducted in many cancer subtypes to examine allele-specific regulation and the TERT mutation." (PMID 32849278, 2020). "Although the two TERT promoter variants are known hotspots in cancer, previously only the C228T variant had been identified in AGCTs." (PMID 32455687, 2020). "Given the key role of telomerase reverse transcriptase (TERT) in cancer, it is essential to understand the mechanism underlying telomerase activation and TERT expression." (PMID 33120984, 2020). "The high prevalence of TERT promoter mutations is found in aggressive thyroid tumors, showing high specificity for malignant neoplasm." (PMID 33247684, 2020). "With the availability of the cBioPortal database, we firstly compared the mutant genes related to sex disparity, and then analyzed the frequency of TERT mutation between different sex groups in different cancer types." (PMID 32915164, 2020). "Recently, several authors documented an association between THOR hypermethylation and cancer progression coupled with TERT upregulation in pancreatic and gastric cancers." (PMID 33329574, 2020). "In our study, we first demonstrated a specific cancer spectrum of TERT mutation and CNA change in 10 336 patients or 10 945 samples to date." (PMID 32810393, 2020). "The telomerase reverse transcriptase (TERT) gene encodes the catalytic subunit of the telomerase complex, which maintains chromosomal ends, thus supporting the immortalization of cancer cells." (PMID 32810393, 2020). "Telomerase reactivation is associated with the alteration of transcriptional regulators of the TERT promoter in cancer, TERT promoter mutations or rearrangements and DNA copy number amplifications." (PMID 32722302, 2020). "Expression of telomerase reverse transcriptase (TERT) and telomerase activity (TA) is a main feature of cancer, contributing to cell immortalization by causing telomeres dysfunction." (PMID 33553285, 2020). "In summary, our findings show that immortalized and cancer cell lines are generally hypermethylated in a region upstream of the recurrent C228T and C250T TERT promoter mutations, while normal primary cells are comparatively hypomethylated." (PMID 32468444, 2020). "We found TERT-promoter mutations with similar frequencies in LNUC compared to conventional carcinomas, with percentages up to 86.7%." (PMID 32213857, 2020). "Studies have identified that the telomerase reverse transcriptase (TERT) gene polymorphism rs10069690 (C>T) is associated with cancer risk, but the results remain inconclusive." (PMID 31454181, 2019). "Due to their prevalence in the disease, understanding the significance of TERT mutations is vital in the understanding of cancer cell growth." (PMID 30795542, 2019).
cancer (continued). "TERT gene promoter mutations (pTERT) increment the transcriptional activities of the TERT and have been connected to malignant tumors with superlative recurrence and lower survival in PTC." (PMID 30916166, 2019). "Further, alternatively spliced variants of TERT, which lack telomerase activity, are capable of inducing the expressions of growth-promoting genes and protect cancer cells from apoptosis." (PMID 31035374, 2019). "Here, we performed a meta‐analysis included 45 case–control studies, including 329,035 cancer cases and 730,940 controls to explore the association between the TERT rs10069690 polymorphism and cancer risk." (PMID 31454181, 2019). "The association between the TERT promoter hypermethylation and poor outcomes or progression was reported in brain tumors, adrenocortical carcinoma, and other cancers." (PMID 31284662, 2019). "In many cancer cells, mutations in the promoter of the gene that encodes for telomerase reverse transcriptase (TERT) causes higher expression rate of TERT." (PMID 31261825, 2019). "Data on age distribution of TERT promoter mutations in pediatric cancers is rare, but a few studies suggest a lower frequency in infants as compared to older children." (PMID 31757062, 2019). "In recent years, TERT promoter mutations have been frequently discovered in human cancers particularly in GBMs23,24." (PMID 30936423, 2019). "This is because we consider only exonic coding mutations here, and additionally TERT promoter mutations, in accord with the latest estimates that non-coding cancer driver mutations appear to be rare." (PMID 30986244, 2019). "The results of this meta‐analysis have shown that the TERT rs10069690 polymorphism is associated with an increased cancer risk overall." (PMID 31454181, 2019). "Studies have identified two cancer-specific TERT promoter mutations (C228T and C250T) in the activation of telomerase in various cancer cells, including GBM." (PMID 30625996, 2019). "These substitution mutations (commonly referred to as C228T and C250T) are to date the most common non-coding mutational events in human cancer, and the mutations alter the affinity for various transcription factors and increase TERT gene output." (PMID 31561592, 2019). "TERT promoter mutations represent a key mechanism for cancer-specific telomerase activation, especially in cancers developing from tissues with low rates of self-renewal." (PMID 30884806, 2019). "TERT promoter mutations were recently reported in thyroid cancer where they have been associated with aggressive cancers." (PMID 31623671, 2019). "We found that the germline variants at the TERT locus significantly affected the TERT promoter mutation rate in HCC patients, and the TERT rs2736100-CC cancer risk genotype was more frequently seen in patients with a wt TERT promoter." (PMID 31285550, 2019). "For those cancers harboring activating TERT promotor mutations, directed immunotherapies have been proposed as part of a personalized treatment." (PMID 31157162, 2019). "Tumors carrying activating mutations in the TERT promoter region tend to be more aggressive, both in head and neck and other cancer types." (PMID 31844556, 2019). "THOR hypermethylation has been found as an alternative telomerase-activating mechanism in cancer that can act independently or in conjunction with TERT promoter mutations, further supporting the utility of THOR hypermethylation as a prognostic biomarker." (PMID 31921291, 2019). "To identify telomerase-associated molecular signatures, we first defined two cancer types based on TERT expression: 1) patients with high expression of TERT (TERThigh) and 2) patients with low expression of TERT (TERTlow)." (PMID 31179925, 2019). "Following the observations of some patients developing distant metastases, we currently offer treatment equivalent to that of malignant tumors for TERT-promoter-mutated FT-UMPs at our institution." (PMID 31561592, 2019).